DSG3 (desmoglein 3)
Description:
A component of desmosome cell-cell junctions which are required for positive regulation of cellular adhesion. Required for adherens and desmosome junction assembly in response to mechanical force in keratinocytes. Required for desmosome-mediated cell-cell adhesion of cells surrounding the telogen hair club and the basal layer of the outer root sheath epithelium, consequently is essential for the anchoring of telogen hairs in the hair follicle. Required for the maintenance of the epithelial barrier via promoting desmosome-mediated intercellular attachment of suprabasal epithelium to basal cells (By similarity). May play a role in the protein stability of the desmosome plaque components DSP, JUP, PKP1, PKP2 and PKP3. Required for YAP1 localization at the plasma membrane in keratinocytes in response to mechanical strain, via the formation of an interaction complex composed of DSG3, PKP1 and YWHAG. May also be involved in the positive regulation of YAP1 target gene transcription and as a result cell proliferation. Positively regulates cellular contractility and cell junction formation via organization of cortical F-actin bundles and anchoring of actin to tight junctions, in conjunction with RAC1. The cytoplasmic pool of DSG3 is required for the localization of CDH1 and CTNNB1 at developing adherens junctions, potentially via modulation of SRC activity. Inhibits keratinocyte migration via suppression of p38MAPK signaling, may therefore play a role in moderating wound healing.
Synonyms: PVA; CDHF6; ABOLM
Tractability: Antibody: UniProt places it where antibodies can reach, with high confidence; its Gene Ontology location is reachable by antibodies, with high confidence; UniProt predicts a signal peptide or a membrane-spanning region. PROTAC: its protein half-life has been measured.
Gene: Protein-coding gene on chromosome 18 (31,447,741 to 31,478,702, forward strand). Ensembl gene ENSG00000134757.
Subcellular location: Cell membrane; Cell junction, desmosome; Cytoplasm; Cell junction, tight junction; Cell junction
Pathways (Reactome):
Developmental Biology: Formation of the cornified envelope; Keratinization
Programmed Cell Death: Apoptotic cleavage of cell adhesion proteins
Gene Ontology:
Molecular function: protein binding; calcium ion binding; protein dimerization activity
Biological process: adherens junction assembly; desmosome assembly; negative regulation of cell migration; negative regulation of p38MAPK cascade; positive regulation of protein localization to adherens junction; positive regulation of protein localization to membrane; regulation of protein stability; tight junction assembly; actin filament organization; cell-cell adhesion; positive regulation of bicellular tight junction assembly; cell adhesion; homophilic cell-cell adhesion
Cellular component: anchoring junction; cell junction; cell-cell junction; cytoplasm; extracellular exosome; plasma membrane; cornified envelope; cytosol; desmosome; tight junction; bicellular tight junction; membrane
Genetic constraint (gnomAD): Loss-of-function variants: 57 observed, 82.4 expected, observed/expected ratio (o/e) 0.69, 90% interval 0.56 to 0.86. The upper end of that interval is the gene's LOEUF score, 0.86, which puts it in group 3 of 6, group 1 being the genes least tolerant of losing a copy. Missense variants: 1,204 observed, 1,245.4 expected, observed/expected ratio (o/e) 0.97, 90% interval 0.92 to 1.01. Synonymous variants: 440 observed, 453.29 expected, observed/expected ratio (o/e) 0.97, 90% interval 0.9 to 1.05.
Homologues: Orthologues: chimpanzee DSG3 (97% identical), macaque DSG3 (96% identical), dog DSG3 (81% identical), pig DSG3 (80% identical), mouse Dsg3 (73% identical), rat Dsg3 (72% identical), tropical clawed frog dsg1 (39% identical). Paralogues in human: DSG4 (49% identical), DSG1 (41% identical), DSG2 (38% identical), DSC2 (25% identical), DSC3 (24% identical), DSC1 (24% identical).
Diseases named in the same sentence as DSG3 in open-access papers:
DSG3 is named in the same sentence as 98 diseases in open-access papers, as found by Europe PMC text mining. Sharing a sentence is not in itself a finding about the gene and the disease. The quoted sentences say what the papers report.
pemphigus (164 papers, 2006 to 2026). Pemphigus is a group of rare autoimmune diseases that cause blistering of the skin and mucous membranes (mouth, nose, throat, eyes, and genitals).This conditioncan occur at any age, but often strikes people in middle or older age. "Elevated CRP level suggested ongoing systemic inflammation, while the raised desmoglein-3 antibody levels indicated autoimmune blistering, favoring a pemphigus variant." (PMID 40809161, 2025). "The primary autoantigens in both forms are Dsg1 and Dsg3, which are considered the most important pathogenic targets in pemphigus." (PMID 40642697, 2025). "Lesion formation of pemphigus is the result of pathogenic autoantibodies that target desmoglein-3 (Dsg3) and desmoglein-1 (Dsg1), located on the surface of epidermal keratinocytes." (PMID 39062594, 2024). "We found that 2G4 induced effects typical for pemphigus pathogenesis including loss of adhesion, keratin filament retraction and fragmentation of Dsg3 staining, which is in line with previous data." (PMID 37143675, 2023). "Several murine pemphigus models were developed subsequently, each allowing the analysis of a characteristic feature, such as pathogenic IgG or Dsg3-specific T or B cells." (PMID 37180099, 2023). "The results give first insights into pemphigus autoantibody-induced Dsg3 epitope-specific signalling which is involved in pathogenic events such as Dsg3 depletion." (PMID 37143675, 2023). "Pemphigus is a life-threatening bullous autoimmune disease in which autoantibodies against Dsg1, Dsg3, Dsc3 as well as other antigens cause flaccid blistering in the epidermis and in mucous membranes of the oral cavity and elsewhere." (PMID 36624106, 2023). "Several murine pemphigus models are available (active, passive), each facilitating the analysis of a characteristic feature, such as pathogenic IgG or Dsg3-specific T or B cells." (PMID 37174740, 2023). "On the other hand, an active disease model of pemphigus expressing anti‐Dsc3 autoantibodies or anti‐Dsc3 and anti‐Dsg3 autoantibodies were developed the pathogenic activity of anti‐Dsc3 autoantibodies." (PMID 36578135, 2023). "Several signaling pathways have been implicated in the downstream effects of DSG1 and DSG3 depletion in pemphigus." (PMID 37237515, 2023). "In this model, DSG3-specific CD4+ T cells induce acantholysis, suggesting that DSG3-specific CD4+ T cells contribute to the generation of pathogenic antibodies in pemphigus." (PMID 37138879, 2023). "Apremilast at a dose between 1 and 100 μM significantly rescued intercellular adhesion in HaCaTs treated with AK23, a pathogenic anti-Dsg3 antibody derived from a pemphigus mouse model and PV2-IgG49." (PMID 36624106, 2023). "Pemphigus is caused by autoantibodies that target desmoglein 1 and desmoglein 3, impacting desmosome function." (PMID 38213911, 2023). "It has been shown that fractions of pemphigus patients’ sera targeting only Dsg3 are sufficient to induce loss of keratinocyte adhesion between the basal and spinous layer of the epidermis (acantholysis) in neonatal mice, a hallmark of pemphigus." (PMID 35634274, 2022). "Pemphigus is a severe autoimmune blistering skin disease disrupting desmosomes and is caused by autoantibodies predominantly against Dsg1 and Dsg3, which finally compromises the integrity of epidermal and mucosal tissue." (PMID 35711465, 2022). "The hallmark of pemphigus is the presence of autoantibodies against the desmosomal cadherins desmoglein 3 (DSG3, in PV) and desmoglein 1 (DSG1, in PF and patients with mucocutaneous PV) on the cell surface of neighboring epidermal keratinocytes." (PMID 35632621, 2022). "The main three pemphigus variants are: Muco-cutaneous pemphigus vulgaris (PV) which shows antibodies against Dsg1 and Dsg3 and affects the epidermis and the mucosa." (PMID 35711465, 2022).
pemphigus (continued). "The most common clinical variant of pemphigus, pemphigus vulgaris (PV), is generally associated with Dsg3 for the mucosal-dominant phenotype, and both Dsg1 and Dsg3 for the mucocutaneous/cutaneous phenotype." (PMID 33796116, 2021). "Pathogenic pemphigus autoantibodies targeting Dsg1 and Dsg3 are mostly directed against EC1 and 2, while antibodies directed for example against EC5 are reported to be non-pathogenic." (PMID 34434944, 2021). "It was shown on a pemphigus experimental model in vivo (neonatal Balb/c mouse model) and in vitro that the immunosorbent can effectively remove desmoglein 3-associated autoantibodies." (PMID 32742728, 2020). "Pemphigus is an autoimmune blistering disease of the skin and mucous membranes caused by autoantibodies against desmoglein 1 (Dsg1) and desmoglein 3 (Dsg3)." (PMID 32509225, 2020). "Pemphigus is driven by pathogenic antibodies to both desmoglein (Dsg) 1 and 3 (PV, mucocutaneous type), or Dsg3 (PV, mucosal dominant-type), or Dsg1 (PF)." (PMID 32642305, 2020). "Pemphigus is an autoimmune disease affecting skin and mucous membranes, with pathogenic autoantibodies directed against desmogleins 1 and 3 (Dsg1 and Dsg3)." (PMID 32158442, 2020). "In contrast, when the AA target desmosomes in the deep layers of the mucosae (i.e., DSG3), deep erosive and vesicular, mucosal-predominant variant of pemphigus (i.e., pemphigus vulgaris [PV]) arises." (PMID 33228633, 2020). "More important, they were less susceptible to direct inhibition by pathogenic pemphigus antibodies than homophilic Dsg3-Dsg3 interactions." (PMID 33193387, 2020). "The importance of Dsg3 in cell-cell adhesion is highlighted by many studies based on pemphigus autoantibodies that demonstrate convincingly that disruption of Dsg3 is a causative factor for the skin and oral lesions." (PMID 31835537, 2019). "The clinical phenotype of pemphigus (i.e., the site of blister formation) is determined by the underlying antibody profile and the normal tissue distribution of Dsg1 and Dsg3." (PMID 31552014, 2019). "Here we tested the effects of PV-IgG and the pathogenic pemphigus mouse anti-Dsg3 antibody AK23 on cytokine secretion and ERK activity in human keratinocytes dependent on ST18 expression." (PMID 31057535, 2019). "In this context, it was demonstrated that autoantibodies from pemphigus patients caused Src-dependent phosphorylation of Pkp3 paralleled by Dsg3 translocation to the cytoplasm and destabilization of cell adhesion." (PMID 31024527, 2019). "Upon the loss of Dsg3 interaction, e.g., by steric hindrance through pemphigus autoantibodies, this suppressive function is abolished and p38MAPK is activated." (PMID 29449846, 2018). "Direct inhibition of Dsg3 interactions is a well-characterized phenomenon in pemphigus which occurs fast after binding of pathogenic autoantibodies but alone is not sufficient to cause complete loss of cell cohesion." (PMID 29616033, 2018). "Pemphigus is a rare life-threatening autoimmune bullous disease, in which the anti-Dsg-1 and anti-Dsg-3 autoantibodies mediate the humoral immune response, causing deep erosions and blisters." (PMID 30083474, 2018). "Their results demonstrated a higher sensitivity and specificity for IIFm (Dsg1: 100%, 100%; Dsg3: 100%, 78%, respectively) compared with IIFc that support the use of IIFm to improve the diagnostic accuracy of pemphigus." (PMID 29872685, 2018). "Next, we investigated depletion of Dsg3 which accompanied loss of intercellular adhesion and was linked to several signaling pathways such as p38MAPK in models of pemphigus." (PMID 29616033, 2018). "Pemphigus is a group of autoimmune skin blistering diseases caused by loss of cell-cell adhesion due to autoantibodies binding to Dsg1 and Dsg3 resulting in the internalization of desmosomes." (PMID 25785582, 2015).
pemphigus (continued). "These events, which at least in part appear to be dependent on autoantibody-induced loss of Dsg3 function impair desmosomal adhesion and finally lead to loss of cell-cell cohesion in pemphigus." (PMID 23326495, 2013). "It was demonstrated previously with the dispase-based dissociation assay that monoclonal antibodies targeting Dsg3 disrupt Dsg3 transinteraction and cause a loss of cell cohesion in cultured keratinocytes as well as in an active pemphigus mouse model." (PMID 23326495, 2013). "Recently, it was shown that p38 MAPK signaling and Dsg3 internalization are linked events in pemphigus acantholysis." (PMID 23226536, 2012). "Significant advances in our understanding of pemphigus pathomechanisms have been derived from the generation of pathogenic monoclonal Dsg3 antibodies." (PMID 23226536, 2012). "A polymorphism of Dsg3 has been observed in association with pemphigus cls II susceptibility alleles, which may contribute to the development of PV." (PMID 40098967, 2025). "This form of pemphigus is associated with autoantibodies directed against the plakin family (envoplakin, periplakin, the desmoplakins) as well as against plectin, 230 BP antigen, plakophilin 3, desmocollin 1, and desmocollin 3, Dsg 1 and Dsg3." (PMID 38256427, 2024). "Pemphigus is a rare autoimmune blistering disease, mediated by a heterogeneous mixture of both pathogenic and non-pathogenic serum IgG mainly directed against the desmosomal adhesion protein Dsg3, a key player in maintaining epidermal integrity." (PMID 39450179, 2024). "Interestingly, Src, which is another well-known Dsg3-dependent signalling protein involved in loss of cell adhesion in pemphigus, was significantly phosphorylated upon treatment with AK23 but not following 2G4 incubation." (PMID 37143675, 2023). "As it has been shown that pathogenic antibodies targeting DSG1 and DSG3 lead to p38MAPK activation in pemphigus, we investigated whether this signaling pathway is activated by AC autoantibodies." (PMID 37450050, 2023). "Furthermore, autoantibodies against DSG1 and DSG3 found in pemphigus cause loss of keratinocyte adhesion, indicating that loss of intercellular adhesion caused by autoantibodies from patients with desmosomal diseases is a hallmark of pathogenicity." (PMID 37450050, 2023). "Pemphigus and bullous pemphigoid (BP) represent the two major types of AIBDs caused by circulating autoantibodies against the desmosomal antigens desmoglein (Dsg) 1 and Dsg3 and hemidesmosomal antigens BP180 and BP230, respectively." (PMID 36203762, 2022). "The serum levels and number of anti-DSG3 IgG subclasses drive the pathogenic effect of pemphigus sera and may predict the occurrence of relapses." (PMID 35371083, 2022). "Finally, another study on biomarkers predictive of relapse in rituximab‐treated pemphigus patients showed that the relapse was associated with positivity for either anti‐Dsg1 or anti‐Dsg3 antibodies in serial ELISA tests after rituximab treatment." (PMID 34288016, 2022). "It was shown that knockout of Dsg3 in mice alone is sufficient to cause a pemphigus-like phenotype." (PMID 34434944, 2021). "Pathogenic autoantibodies in pemphigus are mostly directed against Dsg1 and Dsg3." (PMID 34434944, 2021). "Therefore, we analyzed the heterophilic Dsg2-Dsg3 interactions by cell-free AFM measurements after treatment with AK23, a pathogenic anti-Dsg3 antibody, derived from a pemphigus mouse model." (PMID 33193387, 2020). "Pemphigus is caused by autoantibodies against desmoglein (Dsg) 1, Dsg3, and/or non‐Dsg antigens." (PMID 32815159, 2020). "We hypothesized that the immunodominant P. papatasi salivary protein PpSP32 binds to desmogleins 1 and 3 (Dsg1 and Dsg3), triggering loss of tolerance to these pemphigus target autoantigens." (PMID 33108348, 2020).
pemphigus (continued). "Based on these observations, we speculated that in situations of compromised Dsg3-mediated cell adhesion, e.g., keratin-deficiency or pemphigus, Dsg2 may be capable of compensating for loss of intercellular adhesion." (PMID 33193387, 2020). "Taken together, the data demonstrate that Dsg2 undergoes heterophilic interactions with Dsg3, which may attenuate autoantibody-induced loss of keratinocyte adhesion in pemphigus." (PMID 33193387, 2020). "However, while Dsg3-reactive Th1 cells can be found in healthy individuals carrying PV predisposing HLA class II alleles, Dsg3-reactive Th2 cells are restricted to pemphigus patients." (PMID 31293582, 2019). "Interestingly, changes in the peripheral keratin network occur very rapidly within 1 h after autoantibody incubation and appear to even precede Dsg3 endocytosis, another hallmark of pemphigus." (PMID 29643851, 2018). "Pemphigus is a severe, potentially life-threatening autoimmune disease associated with mucous and cutaneous blisters caused by autoantibodies against cell adhesion proteins desmogleins 1 (Dsg1) and 3 (Dsg3)." (PMID 26417354, 2015). "The pemphigus vulgaris antigen is a 130 kDa protein, Dsg3, which belongs to the cadherin superfamily of calcium-dependent adhesion proteins while Dsg1 is the target of autoantibodies in pemphigus foliaceus, a superficial variant of pemphigus." (PMID 23781320, 2013). "Pemphigus is a family of potentially fatal autoimmune blistering skin diseases caused by autoantibodies directed against desmosomal cadherins desmoglein 1 (Dsg1) and desmoglein 3 (Dsg3)." (PMID 23226536, 2012). "Furthermore, we investigated whether inhibition of ADAMs also play a role in human keratinocyte models for pemphigus, a blistering disease in which autoantibodies mainly against Dsg1 and Dsg3 lead to a loss of cell adhesion." (PMID 35844545, 2022). "The interpretation of the desmoglein compensation theory, as it relates to the clinical findings in pemphigus, can be summarized as follows: patients with antibodies against only desmoglein 3 should have mucosal-dominant PV because desmoglein 1 compensates for the loss of desmoglein 3 in skin." (PMID 34684117, 2021). "Here, we further generated a stable Dsg3-deficient cell line, which showed disturbed cell adhesion and upregulation of Dsg2 in the insoluble, desmosome-containing fraction supporting the observations revealed by immunostaining of ex vivo and pemphigus patient epidermis." (PMID 33193387, 2020). "In pemphigus, autoantibodies against the desmosomal cadherins desmoglein (DSG) DSG1 and DSG3 cause intraepidermal blistering." (PMID 41657310, 2026). "Pemphigus is a severe autoimmune blistering disorder of skin and mucosa, which is elicited by gG autoantibodies targeting desmosomal components such as desmoglein 3 (Dsg3)." (PMID 41491145, 2026). "Analyzing the subtypes of pemphigus, Dsg3 levels were significantly higher in patients with PV than in patients with PF, and Dsg1 antibodies also differed between the two, but not as significantly as Dsg3." (PMID 40661962, 2025). "Among them, 87% of patients with pemphigus were positive for either anti-Dsg1 and anti-Dsg3 antibodies, and 79.25% of patients with BP were positive for either anti-BP180 and anti-BP230 antibodies." (PMID 40661962, 2025). "In PNP, the epitopes within the extracellular domain of Dsg3 are more diffusely distributed, contrasting with the more localized recognition pattern in pemphigus." (PMID 40372624, 2025). "To further clarify the correlation between Dsg1 and Dsg3 and clinical symptoms, we divided patients with pemphigus into PV (Dsg1-Dsg3+, Dsg1+Dsg3+) and PF (Dsg1+Dsg3-)." (PMID 40661962, 2025). "Dsg1, Dsg3, Dsc1-3, mitochondrial proteins and subtypes of the acetylcholine receptor are the major antigens of pemphigus." (PMID 40098967, 2025). "In pemphigus, autoantibodies target Desmoglein 1 (Dsg1) and 3 (Dsg3), desmosomal cadherins that link adjacent keratinocytes." (PMID 40661962, 2025).